EDN3 (endothelin 3)
Diseases named in the same sentence as EDN3 in open-access papers (continued):
Sharing a sentence is not in itself a finding about the gene and the disease.
neuropathy (1 paper, 2020). A disorder affecting the nervous system that manifests with pain, tingling, numbness, and/or muscle weakness. "Various forms of experimental neuropathy induced by peripheral injury have been associated to neurogenic inflammation, eliciting the release of substance P, calcitonin gene-related peptide, neurokinin A, endothelin-3, cytokines, among others cellular mediators of inflammation." (PMID 32457607, 2020).
ovarian carcinoma (1 paper, 2017). A malignant neoplasm originating from the surface ovarian epithelium. "The ovarian cancer cell lines, PEO4 and PEO14, not only express ET-1 (endothelin 1) and ET-3 (endothelin 3) but also ETAR and ETBR, which suggests that ovarian cancer cells stimulate the ETR pathway in an autocrine fashion." (PMID 28439256, 2017).
PCWH syndrome (1 paper, 2025). "Here, we report the histological findings observed in two newborn children: one with clinically defined PCWH syndrome (SOX10; c.769A>T, p.Lys257*) and one with clinically defined WSS (EDN3; c.472C<T, p.Arg158Cys)." (PMID 40364458, 2025).
pulmonary artery hypertension (1 paper, 2013). "Endothelin-3 is implicated in pulmonary artery hypertension and in affecting systemic blood pressure transiently." (PMID 23840332, 2013).
vascular malformation (1 paper, 2025). A non-neoplastic disorder that is the result of defects of vascular morphogenesis. "This analysis suggests that EDN3+ meningeal fibroblasts are closely associated with vascular malformation during SWS progression." (PMID 39921427, 2025).
cancer (15 papers, 2009 to 2025). A tumor composed of atypical neoplastic, often pleomorphic cells that invade other tissues. "EDN3-CPNPs carrying iron (EDN3-CPNPs) can boost the cancer cell-killing efficacy of ferroptosis-assisted CDT to over 80% at higher doses." (PMID 37795022, 2023). "We used several types of assays in this study to investigate the function of EDN3 in cancer biology from different aspects." (PMID 36824133, 2023). "Previous studies have shown that decreased expression or inactivation of EDN3 can inhibit the migration of cancer cells and improve survival." (PMID 36105089, 2022). "Given the promising role of NLGN4X and EDN3 as therapeutic targets and prognostic factors in cancer patients, their predictive value in the discovery set was evaluated." (PMID 34572907, 2021). "In contrast to the potentially oncogenic role of EDN1 and EDN2, there is still little knowledge about the role of EDN3 in cancer initiation or progression." (PMID 19527488, 2009). "The mutation rates of different MHGs varied widely across cancer tissues, with ANK3 having the highest mutation rate (47%), followed by KEL (18%), TRPM7 (16%), KCNA1 (13%), CNNM2 (9%), CNNM1 (9%), TFAP2B (9%), CNNM4 (9%), XK (7%), and EDN3 (5%)." (PMID 41174507, 2025). "EDN3, TFAB2B showed high levels of methylation in almost all cancers, while CNNM1, CNNM2 and KCNA1 showed high levels of methylation in at least half (7 or more) of the cancers." (PMID 41174507, 2025). "Cancers with lower EDNRB expression and higher EDN3 expression would be expected to have most EDNRB receptors saturated by ET3, preventing any ET1-stimulated signaling effects." (PMID 32201539, 2020). "Considering age, several genes responsible for inflammatory protein secretion/activation (KLK3, EDN3), cell-adhesion (PI4KA, AHSAI1) and cancer-related proteins (KLK3, FGFR1/2, PRKACA, and RAC2) were also modulated in AYA-RMS." (PMID 31533233, 2019). "In the case of EDN3, its expression decreased regardless of cancer grade." (PMID 36542159, 2023). "Cancerous tissues yielded a PCR product with primers specific for the unmethylated EDN3 promoter sequence in all cases, due to non-malignant contaminants (stromal cells and endothelial cells) present in the bulk tumour tissue, as has also been described by Suzuki and colleagues." (PMID 19527488, 2009).
tumor (15 papers, 2009 to 2025). "Unfortunately, the number of patients with available clinical data (discovery set = 19) was statistically too low to evaluate the association of NLGN4X and EDN3 expression level with tumor dissemination and patient survival." (PMID 34572907, 2021). "Similarly, researchers separately created CRISPR-mutant zebrafish in which the function of EDN3 or ECE2 in the tumor microenvironment was lost, with both mutations exerting a severe effect on melanocyte development." (PMID 33644052, 2021). "Most of the genes were down-regulated in tumor tissues, for example, EDN3, KCNA1, TFAP2B, and ANK3 genes were significantly down-regulated in KICH, COAD, HNSC, KIRC, THCA, and KIRP." (PMID 41174507, 2025). "For example, transcripts for suppressors TFAP2B AP-2 α/β, HLF (↓7.951 fold) and EDN3 (↓5.932 fold) were decreased in tumor cells compared to basal cells." (PMID 22280838, 2012). "The difference of EDN3 expression between tumours and normal breast tissues was statistically significant (Mann-Whitney U test: P = 0.037; Student unpaired t test: P = 0.039)." (PMID 19527488, 2009). "EDN3 protein was rarely observed in tumour stroma (that is, was detectable only in those stromal cells adjacent to tumour cells with strong EDN3 expression)." (PMID 19527488, 2009). "This downregulation was still evident when comparing EDN3 expression among all tumour and normal breast tissues as illustrated by box plot analysis (P < 0.001) as well as when comparing fold changes of EDN3 expression among the 17 matched pairs." (PMID 19527488, 2009). "EDN3 mRNA expression was assessed by Northern blotting in normal human tissues (n = 9) as well as in matched pairs of normal and tumourous tissues from breast specimens (n = 50)." (PMID 19527488, 2009). "The eight-gene-signature prognostic model (ANGPTL5, CD1B, CD1E, CNTFR, CTSG, EDN3, IL12B, and IL2)-based high- and low-risk groups were significantly related to overall survival (OS), tumor microenvironment (TME) immune cells, and clinical characteristics in LUAD." (PMID 34745015, 2021). "Endothelin-3, a vasoactive peptide released by vascular smooth muscle cells and endothelin converting enzyme-1, a protease that activates endothelin-3 also play a role in angiogenesis and especially in tumor angiogenesis." (PMID 31683667, 2019). "This suggests that a decrease of EDN3 expression accompanied by an increase of EDNRB expression may be a particular feature of gynaecological tumour entities." (PMID 19527488, 2009). "Patients with low EDN3 expression in the tumour had a mean CSS of 99 months (95% confidence interval [CI] 85 to 113 months) as compared with patients with tumours showing high EDN3 expression, which had a prolonged mean CSS of 116 months (95% CI 106 to 126 months)." (PMID 19527488, 2009). "In the group of novel hub genes, low expression levels of UBE2L6, KIR2DL4, IFIT2, and CLEC4E were observed in tumor cells, while high expression levels of SRPX2 and EDN3 were found in SKCM." (PMID 34660598, 2021). "First, we focused on the neuroligin 4 X (NLGN4X) and Endothelin 3 (EDN3) genes, two BPDCN network neural genes, aberrantly upregulated in BPDCN samples and already described in the literature as possibly involved in tumor progression." (PMID 34572907, 2021). "The clinical implication supports the view that EDN3, in contrast to EDN1 and EDN2, may act as natural tumour suppressor in the human mammary gland." (PMID 19527488, 2009). "It has been shown that after metastatic dissemination, keratinocyte-derived endothelin 3 (EDN3) the microenvironment provides signals to promote phenotype switching between invasive and proliferative states and provide proof that targeting tumor cell plasticity is a valuable therapeutic option." (PMID 38419052, 2024).
tumor (continued). "Since the expression DCX and UCHL-1 may increase the ability of BPDCN tumor cells to disseminate to distant organs, globally worsening patient outcome, both genes, as already suggested for NLGN4X and EDN3, may be regarded as possible therapeutic targets to arrest BPDCN dissemination." (PMID 34572907, 2021). "Secondly, at the light of literature findings, among the network-genes related to neurogenesis, the attention was focused on Neuroligin 4 X-linked (NLGN4X) and Endothelin-3 (EDN3), never reported before in BPDCN but already known to correlate with tumor aggressiveness." (PMID 34572907, 2021).
cardiovascular disease (3 papers, 2015 to 2019). "However, none of EDN3 SNPs showed significant association with the susceptibility of developing cardiovascular disease." (PMID 28882114, 2017).
eyelid (1 paper, 2023). "Remarkably, the heterozygous Edn3-null allele mostly rescued both mutant phenotypes, except for the deformity of the incus and the eyelid dysplasia." (PMID 36637912, 2023).
infection (1 paper, 2019). The state of being infected such as from the introduction of a foreign agent such as serum, vaccine, antigenic substance or organism. "We haven’t observed a significant association between the frequencies of both EDN1 and EDN2 genotypes and clinical outcomes, but the rs882345, rs926632 and rs3026575 of EDN3 showed a modest association with hospitalized infection events." (PMID 31167651, 2019).
EDN3 also shares sentences with these, for which no sentence is quoted: megacolon (4 papers); atherosclerosis (3); hemophilia A (3); Stroke (3); end-stage renal disease (2); Peripheral demyelinating neuropathy (2); acute lymphoblastic leukemia (1); adenocarcinoma (1); albinism (1); alopecia (1); angiosarcoma (1); bleeding (1); Bovine mastitis (1); cerebrovascular diseases (1); colorectal cancer (1); congenital sensorineural deafness (1); coronary artery disease (1); diabetes (1); Duchenne muscular dystrophy (1); Dysmyelinating leukodystrophy (1); endothelial dysfunction (1); enteritis (1); essential tremor (1); gastrointestinal stromal tumor (1); glaucoma (1); hearing loss (1); hemophilia (1); hemophilia B (1); Hepatic steatosis (1); hepatocellular carcinoma (1).
A further 18 diseases each share a sentence with EDN3 in 1 paper.